ARPC1B (actin related protein 2/3 complex subunit 1B)
Description:
Component of the Arp2/3 complex, a multiprotein complex that mediates actin polymerization upon stimulation by nucleation-promoting factor (NPF). The Arp2/3 complex mediates the formation of branched actin networks in the cytoplasm, providing the force for cell motility. In addition to its role in the cytoplasmic cytoskeleton, the Arp2/3 complex also promotes actin polymerization in the nucleus, thereby regulating gene transcription and repair of damaged DNA. The Arp2/3 complex promotes homologous recombination (HR) repair in response to DNA damage by promoting nuclear actin polymerization, leading to drive motility of double-strand breaks (DSBs).
Synonyms: ARC41; p40-ARC; p41-ARC; IMD71; PLTEID
Tractability: Small molecule: a structure with a bound ligand is known. PROTAC: ubiquitination databases record sites on it; its protein half-life has been measured.
Gene: Protein-coding gene on chromosome 7 (99,374,226 to 99,394,827, forward strand). Ensembl gene ENSG00000130429.
Subcellular location: Cytoplasm, cytoskeleton; Nucleus
Subcellular location (Human Protein Atlas): Cytosol; Vesicles
Pathways (Reactome):
Developmental Biology: EPHB-mediated forward signaling
Disease: FCGR3A-mediated phagocytosis
Immune System: Regulation of actin dynamics for phagocytic cup formation
Signal Transduction: RHO GTPases Activate WASPs and WAVEs
Gene Ontology:
Molecular function: actin filament binding; protein binding; structural constituent of cytoskeleton; protein-containing complex binding
Biological process: Arp2/3 complex-mediated actin nucleation; cortical actin cytoskeleton organization; response to estradiol; response to estrogen
Cellular component: Arp2/3 protein complex; cytosol; extracellular exosome; focal adhesion; nucleus; actin cytoskeleton; cytoskeleton; tubulobulbar complex
Genetic constraint (gnomAD): Loss-of-function variants: 29 observed, 45.14 expected, observed/expected ratio (o/e) 0.64, 90% interval 0.48 to 0.88. The upper end of that interval is the gene's LOEUF score, 0.88, which puts it in group 3 of 6, group 1 being the genes least tolerant of losing a copy. Missense variants: 469 observed, 522.94 expected, observed/expected ratio (o/e) 0.9, 90% interval 0.83 to 0.97. Synonymous variants: 201 observed, 210.1 expected, observed/expected ratio (o/e) 0.96, 90% interval 0.85 to 1.08.
Gene-disease validity (ClinGen):
ClinGen rates the evidence that ARPC1B causes each of these diseases.
platelet abnormalities with eosinophilia and immune-mediated inflammatory disease (autosomal recessive): Definitive.
Homologues: Orthologues: chimpanzee ARPC1B (99% identical), guinea pig ARPC1B (99% identical), mouse Arpc1b (97% identical), rat Arpc1b (97% identical), dog ARPC1B (96% identical), mouse Gm62072 (95% identical), tropical clawed frog arpc1b (83% identical), rabbit ARPC1B (81% identical), zebrafish arpc1b (81% identical), pig ARPC1B (76% identical), Caenorhabditis elegans arx-3 (51% identical), Drosophila melanogaster Arpc1 (51% identical). Paralogues in human: ARPC1A (68% identical).
Diseases named in the same sentence as ARPC1B in open-access papers:
ARPC1B is named in the same sentence as 73 diseases in open-access papers, as found by Europe PMC text mining. Sharing a sentence is not in itself a finding about the gene and the disease. The quoted sentences say what the papers report.
Immunodeficiency (19 papers, 2019 to 2025). Failure of the immune system to protect the body adequately from infection, due to the absence or insufficiency of some component process or substance. "Wiskott–Aldrich syndrome, Arpc1b deficiency, Hem1 deficiency and numerous other human actinopathies present with elements of autoinflammation and immunodeficiency." (PMID 35681501, 2022). "Kahr and colleagues found that the loss of the ARPC1B subunit causes platelet abnormalities and immunodeficiency and also predisposes to inflammatory disease." (PMID 35681501, 2022). "ARPC1B encodes a subunit of the human Arp2/3 complex involved in the dynamic of the cytoskeleton and the deficiency or loss of which is associated with immunodeficiency." (PMID 35111196, 2021). "Recently, a novel syndrome of combined immune deficiency, allergy, and inflammation has been attributed to mutations in the gene called actin-related protein 2/3 complex subunit 1B (ARPC1B)." (PMID 33679784, 2021). "In conclusion, we have identified a novel mutation of the ARPC1B gene, which leads to combined immune deficiency with recurrent skin and respiratory infections, allergic reactions, asthma, and autoimmunity but not bleeding disorders." (PMID 33679784, 2021). "ARPC1B deficiency can lead to severe combined immunodeficiency with signs of mild bleeding and immune disorder." (PMID 32774561, 2020). "Our study indicates that mutations in ARPC1B will trigger progressive CTL activation–induced immunodeficiency and provides mechanistic insights into the immune dysregulation observed in this disease." (PMID 31710310, 2019). "Patients with mutations in the actin-related protein complex 1B (ARPC1B) subunit of Arp2/3 show combined immunodeficiency, with symptoms of immune dysregulation, including recurrent viral infections and reduced CD8+ T cell count." (PMID 31710310, 2019). "The protein encoded by ARPC1B is one of the subunits of the Arp2/3 protein complex, while the deletion and mutation of the ARPC1B gene disrupt the development of platelets and T-lymphocytes, and leads to a combined immune deficiency encompassing severe infections, inflammations, and allergies." (PMID 36081667, 2022). "In regards to the pathogenesis of the combined immune deficiency phenotype of the three patients described in this study, in silico analysis have shown that the variant c.783G>A of the ARPC1B changes the wild-type donor site and was predicted to be causative in the splicing process." (PMID 33679784, 2021). "Recently, a novel syndrome of combined immune deficiency, infections, allergy, and inflammation has been attributed to mutations in the gene encoding actin-related protein 2/3 complex subunit 1B (ARPC1B), which is a key molecule driving the dynamics of the cytoskeleton." (PMID 33679784, 2021). "Actin-related protein 2/3 complex subunit 1B (ARPC1B) deficiency is a newly characterized syndrome of combined immune deficiency, allergy, and autoimmunity that affects multiple organs due to the crucial role of ARPC1B in the regulation of actin polymerization and the stability of the cytoskeleton." (PMID 33679784, 2021). "Besides, the mutation of ARPC1B is involved in a novel syndrome characterized by immunodeficiency and spontaneous inflammation that may be attributed to Treg and NK cell dysfunction." (PMID 35111196, 2021). "Furthermore, Arpc1B deficiency, due to a homozygous complex frameshift mutation in a combined immunodeficiency patient, led to F-actin polymerization defect and impeded neutrophil movement, thereby suggesting that Arpc1B may govern neutrophil functions via many ways." (PMID 39349750, 2024). "Patient with a homozygous deletion c.212_226del in ARPC1B gene presenting with combined immunodeficiency, recurrent infections, thrombocytopenia, immune dysregulation, and increased radiosensitivity." (PMID 35967303, 2022).
Immunodeficiency (continued). "Although defects in actin polymerization explain several anomalies in chromosomal mobility and immune dysregulation, many aspects of the ARPC1B immunodeficiency are still poorly understood, and its role in DNA repair was never reported." (PMID 35967303, 2022). "There are several reports indicating that mutant ARPC1B plays a significant role in immunodeficiency diseases." (PMID 35185876, 2022). "Mutations in ARPC1B result in defective ARP2/3-dependent actin filament branching, leading to a combined immunodeficiency with severe inflammation." (PMID 34135903, 2021). "Patients lacking ARPC1B show combined immunodeficiency arising from loss of ARPC1B in different hemopoietic cells." (PMID 31710310, 2019). "In this respect, mutations in ARPC1B, ARPC4 and ARPC5, which encode components of the Arp2/3 complex, have been identified as the cause of several genetic disorders, characterised by either immunodeficiency and thrombocytopenia or microcephaly and neurodevelopmental defects." (PMID 40368919, 2025). "The recent identification of immunodeficient patients lacking ARPC1B provides an opportunity to examine the role of Arp2/3 in CTLs, the contribution of CTLs to the immunodeficiency, and the molecular basis of the disease." (PMID 31710310, 2019). "Interestingly, the absence of ARPC1B, a health-specific gene reduced in COVID-19, led to immunodeficiency." (PMID 37956172, 2023).
Thrombocytopenia (10 papers, 2017 to 2026). A reduction in the number of circulating thrombocytes. "The thrombocytopenia observed in Patient 1 indicates that total loss of ARPC1B leads to depression of platelet production and/or increased clearance." (PMID 28368018, 2017). "This classification of ARPC1B deficiency is based on a previously published case series where the majority of patients had bleeding tendency due to thrombocytopenia, and 79% of patients suffered from recurrent or severe bleeding episodes, mostly from the gastrointestinal tract." (PMID 33679784, 2021). "Patients with ARPC1B deficiency have developmental defects and thrombocytopenia." (PMID 34673575, 2021). "Autosomal-recessive pathogenic variants in Actin-related protein 2/3 complex subunit 1B (ARPC1B) result in an inborn error of immunity associated with eczema, thrombocytopenia, leukocytoclastic vasculitis and colitis." (PMID 41793545, 2026). "ARPC1B deficiency leads to combined immunodeficiency (CID) with symptoms of eczema, allergies, inflammation, recurrent infection, and thrombocytopenia." (PMID 41249596, 2025). "ARPC1B-deficient Patients 2 and 3 have normal platelet numbers, while ARPC1B-null Patient 1 has persistent thrombocytopenia." (PMID 28368018, 2017). "Actin-related protein 2/3 complex subunit 1B (ARPC1B) deficiency is a recently described inborn error of immunity (IEI) presenting with combined immunodeficiency and characterized by recurrent infections and thrombocytopenia." (PMID 35967303, 2022).
Autoimmunity (7 papers, 2017 to 2025). The occurrence of an immune reaction against the organism's own cells or tissues. "Similar to cases with ARPC1B variants described previously, our patients suffered from recurrent infections, allergic reactions, asthma, autoimmunity, and failure to thrive." (PMID 33679784, 2021). "Several groups have explored how ARPC1B mutations affect immune cells and lead to a broad immune dysregulation syndrome including susceptibility to infection, allergy, autoimmunity, and autoinflammatory processes." (PMID 33679784, 2021). "These disorders cause disruption of the ARPC1B protein functions, including cytoskeleton rearrangement, formation of immunologic synapses, and chemotaxis, leading to the increased susceptibility to infection, autoimmunity, and allergy seen in our 3 patients." (PMID 33679784, 2021). "However, small differences compounded over time are expected to influence disease and lead to autoimmunity, as is the case in ARPC1B deficiency." (PMID 34673575, 2021). "Deficient ARP2/3 function due to genetic deletion of ARPC1B causes a Wiskott-Aldrich syndrome characterized by a lower threshold for BCR activation, autoimmunity, and an expansion of the transitional B cell compartment." (PMID 39708811, 2025). "Other actin regulatory genes expressed in hematopoietic cells are mutated in autoimmune disorders beyond WAS and ARPC1B deficiency." (PMID 34673575, 2021).
Allergy (6 papers, 2020 to 2025). An allergy is an immune response or reaction to substances that are usually not harmful. "While the IUIS 2022 classification report states that allergy or atopy is characteristic for these conditions, it does not do so for ARPC1B, PLCG2, and IL6ST deficiencies – all of which had a high prevalence of allergy in our study." (PMID 41142799, 2025). "The highest prevalence of allergy was found in patients suffering from genetic disorders caused by variants in DOCK8, CARD11 (AD DN), ARPC1B, and PLCG2, while there were no occurrences of allergy in patients with defects in the LRBA and RAG1 genes." (PMID 41142799, 2025).
ovarian carcinoma (6 papers, 2015 to 2025). A malignant neoplasm originating from the surface ovarian epithelium. "Further research is needed to explore the effects of ARPC1B on the cell cycle in ovarian cancer and its underlying mechanisms." (PMID 37304283, 2023). "Future studies should focus on examining a greater number of tissue samples using immunohistochemistry to further validate the diagnostic value of ARPC1B and exploring the impact of ARPC1B on the tumor microenvironment, metabolism, drug resistance, and radiotherapy resistance in ovarian cancer." (PMID 37304283, 2023). "Prior research has demonstrated that ARPC1B facilitates ovarian cancer progression via activation of the Wnt/β-catenin cascade." (PMID 41050079, 2025). "that elevated ARPC1B expression in ovarian cancer facilitates tumor development through the Wnt/β-catenin signaling pathway." (PMID 39867911, 2024). "To investigate the effect of ARPC1B on ovarian cancer progression, we modulated its expression in ovarian cancer cell lines SKOV3 and A2780." (PMID 37304283, 2023). "The expressions and prognostic value of ARPC1B in ovarian cancer were identified using the GEPIA database and the Kaplan-Meier Plotter database." (PMID 37304283, 2023). "The expression of ARPC1B was manipulated to evaluate its impact on the malignant phenotypes of ovarian cancer." (PMID 37304283, 2023). "The overexpression of ARPC1B promoted cell proliferation, migration, and invasion of ovarian cancer cells." (PMID 37304283, 2023). "Further research is needed to fully understand the mechanism by which ARPC1B activates the Wnt/β-catenin signaling pathway in ovarian cancer cells and to assess the potential therapeutic value of targeting ARPC1B." (PMID 37304283, 2023). "Conversely, overexpression of ARPC1B leads to a more significant increase in the proliferation and migration abilities of ovarian cancer cells in A2780 cells than in SKOV3 cells." (PMID 37304283, 2023). "Our results suggested the possibility that the overexpression of ARPC1B promoted the expression of cell proliferation or metastasis-related proteins by the activation of the Wnt/β-Catenin signaling pathway in ovarian cancer." (PMID 37304283, 2023). "The overexpression of ARPC1B has been shown to contribute to the malignant phenotype in ovarian cancer via activation of the Wnt/β-Catenin signaling pathway." (PMID 37304283, 2023). "The results demonstrated that ARPC1B was significantly overexpressed in ovarian cancer tissues compared to normal ovarian tissues, and significantly overexpressed in ovarian cancer cell lines compared to ovarian epithelial cell line." (PMID 37304283, 2023). "In this study, we have discovered that ARPC1B promotes the progression of ovarian cancer by activating the Wnt/β-Catenin signaling pathway." (PMID 37304283, 2023). "In this study, we conducted a bioinformatics analysis and found that the expression of ARPC1B was overexpressed in ovarian cancer." (PMID 37304283, 2023). "Our findings in vivo confirmed that ARPC1B overexpression facilitated the growth of ovarian cancer xenograft tumors, while ARPC1B interference suppressed tumor growth." (PMID 37304283, 2023). "Our data suggested that ARPC1B was overexpressed in ovarian cancer, which was correlated with a poorer survival compared to low mRNA expression of ARPC1B in ovarian cancer patients." (PMID 37304283, 2023). "We then explored the effects of modulating ARPC1B expression on ovarian cancer cells and found that it significantly influenced cell proliferation, metastasis, and invasion in vitro, as well as the growth of ovarian cancer tumors in vivo." (PMID 37304283, 2023). "In this work, we conducted a bioinformatics analysis and found that the expression of ARPC1B was significantly elevated in ovarian cancer patients." (PMID 37304283, 2023). "The purpose of this study is to explore the mechanism of Actin Related Protein 2/3 Complex Subunit 1B(ARPC1B) in the progression of ovarian cancer." (PMID 37304283, 2023).
ovarian carcinoma (continued). "Our results showed that ARPC1B was significantly overexpressed in ovarian cancer tissues compared to normal tissues." (PMID 37304283, 2023). "The survival analysis indicated that a high expression level of ARPC1B was associated with poorer overall survival and progression-free survival in ovarian cancer patients, suggesting the prognostic significance of ARPC1B." (PMID 37304283, 2023). "Elevated ARPC1B expression has been reported in various cancers, correlating with increased malignancy, invasiveness, and poorer clinical outcomes in prostate cancer, ovarian cancer, and glioblastoma." (PMID 41050079, 2025). "This is the first report to suggest that ARPC1B is involved in ovarian cancer progression and may act as an oncogene in ovarian cancer." (PMID 37304283, 2023). "The expression levels of ARPC1B were found to be elevated in ovarian cancer tissues." (PMID 37304283, 2023). "Interestingly, our results suggest that knocking down ARPC1B leads to a more significant decrease in the proliferation and migration abilities of ovarian cancer cells in SKOV3 cells than in A2780 cells." (PMID 37304283, 2023). "ARPC1B promoted ovarian cancer progression through activation of Wnt/β-catenin Signaling Pathway." (PMID 37304283, 2023). "ARPC1B was overexpressed in ovarian cancer and was correlated with poor prognosis." (PMID 37304283, 2023). "We determined the mRNA and protein expression of ARPC1B in ovarian tissue and ovarian cells, including ovarian epithelial cell line IOSE80 and ovarian cancer cell lines A2780, CAOV3, and SKOV3." (PMID 37304283, 2023). "Despite its known role in other types of cancer, the role of ARPC1B in ovarian cancer has not yet been reported in the literature." (PMID 37304283, 2023).
eczema (5 papers, 2017 to 2026). "Our results indicate that near-complete loss of ARPC1B expression results in platelet abnormalities including microthrombocytes and spreading defects, and also eczema, leukocytoclastic vasculitis, eosinophilia and elevated IgA and IgE." (PMID 28368018, 2017).
eosinophilia (5 papers, 2017 to 2025). "Manifestations of immune dysregulation, including colitis, vasculitis, and severe dermatitis, associated with eosinophilia, hyper-IgA, and hyper-IgE are also described in ARPC1B-deficient patients." (PMID 35967303, 2022). "Here we show in a child with microthrombocytopenia, eosinophilia and inflammatory disease, a homozygous frameshift mutation in ARPC1B (p.Val91Trpfs*30)." (PMID 28368018, 2017). "Moreover, almost complete loss of ARPC1B expression leads to platelet defects, including microthrombus formation and spreading defects, as well as eczematous lesions, leukocyte fragmentation, vasculitis, eosinophilia, and increased IgA and IgE levels." (PMID 40718484, 2025). "Thus ARPC1B deficiency in humans results in defective Arp2/3 actin filament branching that is associated with multisystem disease including platelet abnormalities, cutaneous vasculitis, eosinophilia and predisposition to inflammatory diseases." (PMID 28368018, 2017). "ARPC1B (Actin Related Protein 2/3 Complex Subunit 1B) has been found to be involved in platelet abnormalities of immune-mediated inflammatory disease and eosinophilia." (PMID 35163398, 2022).